IL2 (interleukin 2)
Diseases named in the same sentence as IL2 in open-access papers (continued):
Sharing a sentence is not in itself a finding about the gene and the disease.
tumor (continued). "However, macrophage inhibition during IL-2/anti-CD40 immunotherapy in young mice led to tumor outgrowth and only 43% survival." (PMID 30459812, 2018). "Nevertheless, despite TNF-α, INF-γ, and IL-2 possessing anti-tumor potency, the systemic clinical applications of high doses of these drugs are severely limited due to their systemic toxicities, for instance, inflammatory response, and underlying cardiotoxicity." (PMID 30483132, 2018). "In addition, administration of live M. smegmatis was administered to mice to produce Th1-type cellular responses (IFN-γ and IL-2) and anti-tumor effects." (PMID 29988402, 2018). "Taking into account that Avelumab treatment in combination with IL-2 or IL-15 may result in tumor cells being exposed to higher levels of IFN-γ derived from NK cells or CD8 T cells; we further studied in vitro the effect of combining both treatments." (PMID 30294328, 2018). "Herein, we investigated the efficacy of IL-2/CD40 treatment in elderly tumor-bearing mice." (PMID 30560130, 2018). "Collectively, these changes may contribute to the IL-2/CD40-induced slowing of tumor growth observed in both age groups." (PMID 30560130, 2018). "In addition to the neo-antigen release and inflammatory response from the virus, the IL-2 acts in the tumour microenvironment to expand tumour-specific T-cells while limiting the severe life-threatening side effects associated with systemic IL-2." (PMID 30410056, 2018). "IL-21 can potentiate the expansion and anti-tumor activity of IL-2 stimulated NK cells." (PMID 30546366, 2018). "Major studies suggest that administration of exogenous IL-2 may be necessary for the anti-tumor activity for the first-generation CAR T cells that lack costimulatory domains." (PMID 29980239, 2018). "Additionally, we observed that mice with low level of local IL-2 (in tumor sections) presented larger tumors." (PMID 30687269, 2018). "Given that CEACAM1 expression on both immune cells and tumor cells is reported to be upregulated following activation by IL-2 or tumor cell contact, we also investigated whether anti-PD-1 treatment enhances CEACAM1 expression on CD8+ T cells." (PMID 30349641, 2018). "One explanation for this unique toxicity could be that the immune response initiated by either genetically engineered T-cells or tumor vaccine, respectively, was somehow reactivated or enhanced by HD IL-2." (PMID 29898784, 2018). "Here, we summarize and discuss the most relevant reported studies with a focus on: (a) the effects of IL-2 immunocytokines on innate and adaptive anti-tumor immune cell responses as well as immunosuppressive Treg cells and (b) the approaches to circumvent IL-2-mediated severe toxic side effects." (PMID 30619269, 2018). "In an attempt to reduce the severe toxic side effects caused by systemic exposure of high-dose IL-2, we used as a backbone a thymidine kinase (TK), and vaccinia growth factor (VGF) deficient oncolytic vaccinia virus (vvDD) to deliver membrane-bound IL-2 into the tumour microenvironment." (PMID 30410056, 2018). "To assess if L. casei strain BL23 could exerted its anti-tumor effects via IL-2, we first investigated its abilities to induce IL-2 expression in an in vitro model of BMDCs." (PMID 30687269, 2018). "Which of these mechanisms is more important for tumor rejection remains unclear, however the predominant dependence of murine anti-tumor activity and human IL-2 production (SEB assay) on CD4+ cells is intriguing." (PMID 30563566, 2018). "IL-2 immunocytokines have been developed both to avoid these undesired clinical side effects, and to target cancer cells with specific anti-tumor antibodies fused with IL-2 that can elicit a potent anti-tumor immunological response within the immunosuppressive TME." (PMID 30619269, 2018). "The high affinity of IL-2Rα for IL-2 led us to hypothesize that IL-2Rα up-regulation may promote tumor cell proliferation and progression." (PMID 30340635, 2018).
tumor (continued). "It is reported that, Natural killer cells as well as T-cells expresses cytokines such as interferon-γ (IFN-γ), tumor necrosis factor-α (TNF-α) and interleukin-2 (IL-2) which in turn can induce PD-L1 expression on surrounding immune and tumor cells when T-cells recognize antigen and become activated." (PMID 29409471, 2018). "However, we did examine CD8+ T-cells from the tumor-draining axillary lymph node, where we found an increase in intracellular IL-2 production, one of the most important cytokines involved in cytotoxic T-cell activation and clonal proliferation." (PMID 29777149, 2018). "This may be enhancing cytokine and tumor activation such as by IL-2 and K562 feeder cells, thereby alleviating cytokine-induced death." (PMID 30400618, 2018). "Several studies have investigated IL-2 for potential use in tumor growth inhibition." (PMID 30687269, 2018). "All these data suggested that tumor growth could influence the production and secretion of serum IL-2, TNF-α and IFN-γ, while PPs could enhance the immune function by stimulating the expression of serum cytokines in S180-bearing mice." (PMID 30966454, 2018). "For 15 years, several works have investigated IL-2 for potential use in tumor growth inhibition." (PMID 30687269, 2018). "In addition, IL-2 activated NKs induced higher CD107a exposure in the presence of RCC autologous tumor cells or A498 as compared to SN12C (average CD107a+NK: 4.7 and 2.7% vs 0.3% respectively at 10E:1 T ratio)." (PMID 30514329, 2018). "Along this line, NK cell isolated from the tumor and cultured with IL-2, could still be triggered via CD16, besides through the engagement of other NK cell activating receptors, including NKG2D." (PMID 29910806, 2018). "Thus, the Tag7-activated CD3+CD4+ subpopulation of lymphocytes was only able to kill HLA-negative tumor cells, as has also been demonstrated for the cytokine IL-2-activated lymphocytes." (PMID 29850628, 2018). "Indeed, primary NK cells with high frequency of NKG2D and low frequency of CD158a stimulated by FSD13 exhibited significantly higher cytotoxicity on K562 tumor cells than those exposed to wild-type IL-2." (PMID 30250191, 2018). "Therefore, the chronic co-stimulation of NK cells with IL-2 and TGFβ during cytokine and tumor activation represents a novel setting in which TGFβ induces pro-inflammatory NK cells." (PMID 30400618, 2018). "Importantly, a pharmacodynamic biomarker of tumor rejection was identified by coordinated elevations in serum IFNγ, IL-2, IL-4, IL-5, IL-6 and IL-17A." (PMID 30400822, 2018). "Interestingly, we also detected a positive correlation between local levels of CD3+ cells and IL-2 in tumor-bearing mice (r2 = –0.83, p < 0.0001)." (PMID 30687269, 2018). "Thus, reports on use of IL-2 have used two different strategies, one to reduce the autoimmune responses and another to augment immune responses against tumor." (PMID 29854806, 2018). "Furthermore, our data from tumor cell metastases and transplantation models in mice show that FSD13 has more tumor suppressive effects than wild-type IL-2." (PMID 30250191, 2018). "IL-2/CD40 mostly did not alter young or elderly tumor-associated DC subset proportions, relative to untreated mice, with the exception of a small, but significant, increase in cross-presenting CD8α+CD11b− cDCs in elderly tumors." (PMID 30560130, 2018). "IL-2 has been demonstrate to play an crucial role in tumor proliferation." (PMID 30045697, 2018). "As the age-related differences in TDLN and tumor-infiltrating CD11c+ cells and T cells reported in this study were observed after one-third of the usual IL-2/CD40 schedule, further studies are required to examine CD11c+ cells/DCs and T cells after a complete schedule of IL-2/CD40." (PMID 30560130, 2018).
tumor (continued). "In a small cohort of MM patients, we were able to isolate autologous tumor cells, and we could demonstrate that IL-2/15 stimulated autologous NK cells were able to significantly improve their killing capacity of autologous tumor cells." (PMID 30542346, 2018). "IL-2 also plays a vital role in anti-tumour activity and immune regulation." (PMID 29459629, 2018). "Hence, MIF seems to favor tumor growth by increasing Treg generation, through the modulation of IL-2 production." (PMID 29707160, 2018). "Thus, clonal repopulation of T cells directed against overexpressed self-derived differentiation antigens, in combination with chemotherapy and high doses of IL-2, led to tumor regression in patients with metastatic melanoma." (PMID 29403496, 2018). "Salmonella induced upregulation of Il2, Il4, Ifng, and Tnfa gene expression in the tumor, which might be involved in the intratumoral recruitment of CD4+ T, CD8+ T, and NK cells." (PMID 29410666, 2018). "So we determined the local IL-2 expression (in tumor sections) of mice bearing tumors by qPCR." (PMID 30687269, 2018). "These authors hypothesize that the IL-2 immunocytokine and RT could elicit an immune-mediated abscopal effect with tumor regression far from the irradiated tumor field." (PMID 30619269, 2018). "Taken together these results suggest that IL2 has potential as an anti-cancer treatment by activation of tumor targeting immune cells, but its use in the clinic has been greatly hampered by its toxicity profile, especially when it was administered systemically." (PMID 29467958, 2018). "Similarly, treatment of patients with uveal melanoma by adoptive transfer of autologous TIL, administered together with IL-2, resulted in objective tumor regression." (PMID 29403496, 2018). "In the case of gene-modified T cell immunotherapies also—for e.g., when patient T cells are bioengineered to express chimeric antigen receptors or TCRs directed against select tumor antigens–IL-2 is critical for expansion of CAR T cells to sufficient numbers for therapeutic benefit." (PMID 30619342, 2018). "Examination of tumor-associated T cells showed that IL-2/CD40 reduced young, but not elderly, CD4+ T cell and Treg proportions, leaving elevated Treg proportions in elderly IL-2/CD40-treated tumors, implying increased suppressive activity in elderly tumors." (PMID 30560130, 2018). "Nonetheless, IL-2/CD40 was less effective in elderly tumor-bearing mice, which could be attributed to an exacerbated suppressive environment in elderly TDLNs." (PMID 30560130, 2018). "The anti-tumor function of IL-2 therapy is known to directly activate CTLs." (PMID 30533489, 2018). "Furthermore, some IL-2 immunocytokines have been largely shown to trigger tumor cell killing by antibody dependent cellular cytotoxicity (ADCC), through Fcγ receptors engagement." (PMID 30619269, 2018). "Inactivation of EZH2 in this context produced a synergistic effect with CTLA-4 and IL-2, suppressing tumor growth, which suggests that EZH2 expression may serve as an immune escape mechanism during immunotherapy." (PMID 30497521, 2018). "Thus, in multiple tumor models immunoliposome therapy maintained the anti-tumor efficacy but eliminated multiple features of the systemic toxicity elicited by free IL-2-Fc + anti-CD137 treatment." (PMID 29295974, 2018). "Here, according to the literature reviewing, we summarized and discussed: (a) the effects of IL-2 immunocytokines on innate and adaptive anti-tumor immune response and (b) their use in combination with other immunocytokines, chemio- and radio-therapy, immune checkpoint blockade, and immunotherapies." (PMID 30619269, 2018). "In order to determine whether CTL activity was altered during aging following macrophage depletion and immunotherapy, we next performed in vivo CTL analyses in AE17sOVA tumor-bearing mice ± IL-2/anti-CD40 immunotherapy ± macrophage depletion." (PMID 30459812, 2018).
tumor (continued). "Tumor samples were available from 14 (out of 19) patients and we successfully expanded TILs from all patients using standard culture conditions (i.e., high-dose IL-2)." (PMID 29545564, 2018). "Moreover, in an autologous setting, IL-2 activated NKs isolated from RCC-VHL-MUT patients more efficiently degranulated toward RCC autologous tumor cells or A498 VHL-MUT cells as compared to SN12C (RCC-VHL-WT) cell line." (PMID 30514329, 2018). "Once bound to the target tumor, the interleukin-2 (IL-2) immunocytokines composed of either full antibody or single chain Fv conjugated to IL-2 can promote the in situ recruitment and activation of natural killer (NK) cells and cytotoxic CD8+ T lymphocytes (CTL)." (PMID 30619269, 2018). "During dissection of the mice, the investigator found that tumor cells had spread widely via blood circulation and adjacent invasion to areas such as the chest wall and right kidney in the control and wild-type IL-2 groups, but such widely spaced nodules were seldom found in the FSD13 group." (PMID 30250191, 2018). "To test whether patient-derived immune components co-exist in PDXs, we cultured PDX tumor tissues for TILs in vitro by adding human interleukin-2 (IL-2) to the medium." (PMID 30477533, 2018). "However, the mechanism of action of this drug inhibits FKBP by decreasing the levels of IL-2, thereby decreasing the inflammatory microenvironment and the immune response in the tumor." (PMID 30208561, 2018). "Moreover, IL-2 and IL-15 stimulation of NK cells enhanced Avelumab-triggered cytokine production and degranulation along with increased lytic activity against tumor cells." (PMID 30294328, 2018). "Regardless of age, IL-2/CD40 up-regulated CD25 on tumor-associated CD8+ T cells relative to PBS controls, this increase was more striking in young mice." (PMID 30560130, 2018). "Despite preserving a higher proportion of early/central memory subsets that mediate improved tumor immunity in mice, transfer of Vγ2Vδ2 T cells expanded with IL-15 inhibited PC-3 tumor growth in NSG mice identically to equal numbers of Vγ2Vδ2 T cells expanded with IL-2." (PMID 28239463, 2017). "Previous studies have shown that administration of an IL-2 mutant (H9, superkine) could reverse NK cell ‘anergy’ in vivo, which is induced in MHC-I-deficient tumor environments." (PMID 29222435, 2017). "In contrast to EOC cell-free ascites, ascites with EOC cells displayed an immunosuppressive tumor microenvironment, with high contents of T-reg lymphocytes, down-regulation of NK cell-activating receptors and NK hyporesponsiveness to IL-2 stimulation, as demonstrated by the degranulation assay." (PMID 28513532, 2017). "These cells prevent antitumor lymphocyte activity and tumor eradication, and was found to be correlated with poor clinical response, numerous IL-2 mutants (superkines) are under development to replace the native IL-2 and limit this undesired effect." (PMID 28927416, 2017). "Our control group received the tumour cell injection with a daily IL-2 dose." (PMID 28668076, 2017). "TNFa may locally induce an immune response against ED-B+ tumor cells, while the IL-2 moiety may locally activate CTL, NK cells, and macrophages." (PMID 29312320, 2017). "Mice treated with adoptively transferred human NK cells show NK-mediated rejection of the engrafted human tumor and further administration of cytokines, such as IL-2 and IL-15 greatly improve the NK cell pool and their cytotoxic activity against transformed cell." (PMID 28405194, 2017). "Indeed, IL-2 administration has been shown to increase Treg numbers in cancer patients and in murine tumour models." (PMID 28239749, 2017). "The different treatments, including IFNα, IL2 and combinations thereof, might have induced or boosted the effector functions of tumour-reactive CD8+ T cells, favouring mutant outgrowth." (PMID 28561041, 2017).
tumor (continued). "On the one hand, IL-2-stimulated CD226−/− NK cells could perform missing self-reactions against tumour cells in vitro, while on the other hand CD226−/− mice exhibited slightly reduced capacity for missing self rejection of MHC-I− cells in vivo." (PMID 28561023, 2017). "We found that intratumoral transfer of IL-7 effectors but not IL-2 effectors caused a significant regression of tumor size in Treg-replete tumor-bearing mice." (PMID 28496990, 2017). "This combination immunotherapy required a T cell vaccine, tumor-targeting-antibody, recombinant IL-2, and anti-PD-1 blockade, which induced recruitment of tumor infiltrating immune cells and production of intratumoral proinflammatory cytokines in a genetically engineered murine melanoma." (PMID 28265580, 2017). "Results showed successful targeting efficiency of ACT cells with low binding to endogenous T cells in both cases; however IL-2-loaded nanoparticles were also able to induce repeated waves of ACT T cell expansion in tumor-bearing mice upon multiple injections, thanks to IL-2 signalling." (PMID 28629381, 2017). "IL-2 is also involved in immune responses, antibody reactions, and tumor immune surveillance." (PMID 29348890, 2017). "Treatment with NK-activating cytokines, IL-12 and IL-18, or with an IL-2 mutant (H9 “superkine”) increased survival of MHC-I-deficient tumor-bearing mice, accompanied by restoration of effector functions of MHC-I-deficient tumor-infiltrating NK cells." (PMID 28702032, 2017). "In vivo adoptive immunotherapy (AIT) experiments demonstrated anti-tumor efficacy was equally effective using IL-2, IL-21, IL-2/21, IL-7/15 and IL-7/15/21-cultured lymphocytes vs. control or cyclophosphamide alone, even at lower doses or with greater initial size of tumor prior to treatment." (PMID 28146052, 2017). "In addition, there have been previous reports of an additive effect of IL‐2 and GM‐CSF in several tumor models." (PMID 28205361, 2017). "It is well known that cancer cells might encounter IFN-γ produced by activated T cells in the tumor's local microenvironment, and thus could respond by upregulating PD-L1 on their cell membrane to suppress T cell secretion of IL-2." (PMID 28404966, 2017). "It is found that the anti-tumor effect of APS on H22 tumor-bearing mice might be related to its ability to enhance the expression of IL-1, IL-2, IL-6 and TNF-α and decrease of IL-1040." (PMID 28303957, 2017). "Interestingly, T cells expanded by co-electroporation of OKT3-28BB with CD86 and 4-1BBL showed less differentiated phenotypes, although they still maintained a tumor lytic ability as potent as that of OKT3/IL-2-stimulated T cells." (PMID 28523432, 2017). "Therefore, achieving the proper balance between beneficial IL-2 stimulation of Teff cells vs. suppressive Treg conditions not only anti-tumor effects but also treatment-limiting toxicities." (PMID 29176694, 2017). "This decreased IL-2 production and increased lytic activity in the OKT3/IL-2 T cells suggests that the OKT3/IL-2 T cells are more differentiated toward effector memory cells, with increased direct tumor-controlling ability and decreased migration and proliferation potential." (PMID 28523432, 2017). "Our results demonstrate that BsAb can rescue PD-L1/PD-1-mediated inhibition of IL-2 in a tumor microenvironment, which may play an important role in activating effector T cells by blocking PD-L1/PD-1 signaling." (PMID 28404966, 2017). "For example, TFs, such as ASH1L, CFLAR, HMGB3, ZNF160 and MATR3, displayed opposite behaviors on some cytokines; inflammatory factors; nuclear and tumor factors, such as IL-2, IL-6, NF-κB, and Irf3; immunogenic nucleic acids; papillomavirus E7/E6; caspase-3/caspase-8; Toll-like receptor; and so on." (PMID 28719625, 2017).